IGF2BP1 (insulin like growth factor 2 mRNA binding protein 1)
Description:
RNA-binding factor that recruits target transcripts to cytoplasmic protein-RNA complexes (mRNPs). This transcript 'caging' into mRNPs allows mRNA transport and transient storage. It also modulates the rate and location at which target transcripts encounter the translational apparatus and shields them from endonuclease attacks or microRNA-mediated degradation. Preferentially binds to N6-methyladenosine (m6A)-containing mRNAs and increases their stability. Plays a direct role in the transport and translation of transcripts required for axonal regeneration in adult sensory neurons (By similarity). Regulates localized beta-actin/ACTB mRNA translation, a crucial process for cell polarity, cell migration and neurite outgrowth. Co-transcriptionally associates with the ACTB mRNA in the nucleus. This binding involves a conserved 54-nucleotide element in the ACTB mRNA 3'-UTR, known as the 'zipcode'. The RNP thus formed is exported to the cytoplasm, binds to a motor protein and is transported along the cytoskeleton to the cell periphery. During transport, prevents ACTB mRNA from being translated into protein. When the RNP complex reaches its destination near the plasma membrane, IGF2BP1 is phosphorylated. This releases the mRNA, allowing ribosomal 40S and 60S subunits to assemble and initiate ACTB protein synthesis. Monomeric ACTB then assembles into the subcortical actin cytoskeleton (By similarity). During neuronal development, key regulator of neurite outgrowth, growth cone guidance and neuronal cell migration, presumably through the spatiotemporal fine tuning of protein synthesis, such as that of ACTB (By similarity). May regulate mRNA transport to activated synapses (By similarity). Binds to and stabilizes ABCB1/MDR-1 mRNA (By similarity). During interstinal wound repair, interacts with and stabilizes PTGS2 transcript. PTGS2 mRNA stabilization may be crucial for colonic mucosal wound healing (By similarity). Binds to the 3'-UTR of IGF2 mRNA by a mechanism of cooperative and sequential dimerization and regulates IGF2 mRNA subcellular localization and translation. Binds to MYC mRNA, in the coding region instability determinant (CRD) of the open reading frame (ORF), hence preventing MYC cleavage by endonucleases and possibly microRNA targeting to MYC-CRD. Binding to MYC mRNA is enhanced by m6A-modification of the CRD. Binds to the 3'-UTR of CD44 mRNA and stabilizes it, hence promotes cell adhesion and invadopodia formation in cancer cells. Binds to the oncofetal H19 transcript and to the neuron-specific TAU mRNA and regulates their localizations. Binds to and stabilizes BTRC/FBW1A mRNA. Binds to the adenine-rich autoregulatory sequence (ARS) located in PABPC1 mRNA and represses its translation. PABPC1 mRNA-binding is stimulated by PABPC1 protein. Prevents BTRC/FBW1A mRNA degradation by disrupting microRNA-dependent interaction with AGO2. Promotes the directed movement of tumor-derived cells by fine-tuning intracellular signaling networks. Binds to MAPK4 3'-UTR and inhibits its translation. Interacts with PTEN transcript open reading frame (ORF) and prevents mRNA decay. This combined action on MAPK4 (down-regulation) and PTEN (up-regulation) antagonizes HSPB1 phosphorylation, consequently it prevents G-actin sequestration by phosphorylated HSPB1, allowing F-actin polymerization. Hence enhances the velocity of cell migration and stimulates directed cell migration by PTEN-modulated polarization. Interacts with Hepatitis C virus (HCV) 5'-UTR and 3'-UTR and specifically enhances translation at the HCV IRES, but not 5'-cap-dependent translation, possibly by recruiting eIF3. Interacts with HIV-1 GAG protein and blocks the formation of infectious HIV-1 particles. Reduces HIV-1 assembly by inhibiting viral RNA packaging, as well as assembly and processing of GAG protein on cellular membranes. During cellular stress, such as oxidative stress or heat shock, stabilizes target mRNAs that are recruited to stress granules, including CD44, IGF2, MAPK4, MYC, PTEN, RAPGEF2 and RPS6KA5 transcripts.
Synonyms: IMP-1; IMP1; CRD-BP; CRDBP; VICKZ1; ZBP1
Tractability: Small molecule: it has a high-quality binding pocket. PROTAC: ubiquitination databases record sites on it; a small molecule that binds it is known.
Gene: Protein-coding gene on chromosome 17 (48,997,225 to 49,056,145, forward strand). Ensembl gene ENSG00000159217.
Subcellular location: Nucleus; Cytoplasm; Cytoplasm, perinuclear region; Cytoplasm, P-body; Cytoplasm, Stress granule; Cell projection, lamellipodium; Cell projection, dendrite; Cell projection, dendritic spine; Cell projection, growth cone; Cell projection, filopodium; Cell projection, axon
Subcellular location (Human Protein Atlas): Cytosol
Pathways (Reactome):
Metabolism of RNA: Insulin-like Growth Factor-2 mRNA Binding Proteins (IGF2BPs/IMPs/VICKZs) bind RNA
Signal Transduction: MAPK6/MAPK4 signaling
Gene Ontology:
Molecular function: mRNA 3'-UTR binding; mRNA 5'-UTR binding; mRNA binding; N6-methyladenosine-containing RNA reader activity; protein binding; RNA binding; translation regulator activity; nucleic acid binding
Biological process: CRD-mediated mRNA stabilization; negative regulation of nuclear-transcribed mRNA catabolic process, deadenylation-dependent decay; negative regulation of translation; positive regulation of cytoplasmic translation; regulation of mRNA stability involved in response to stress; regulation of stress granule assembly; nervous system development; regulation of cytokine production; dendrite arborization; RNA localization
Cellular component: CRD-mediated mRNA stability complex; cytoplasm; cytoplasmic stress granule; cytosol; P-body; ribonucleoprotein complex; axon; dendrite; dendritic spine; filopodium; growth cone; lamellipodium; neuronal cell body; nucleus; perinuclear region of cytoplasm
Genetic constraint (gnomAD): Loss-of-function variants: 7 observed, 69.39 expected, observed/expected ratio (o/e) 0.1, 90% interval 0.056 to 0.19. The upper end of that interval is the gene's LOEUF score, 0.19, which puts it in group 1 of 6, group 1 being the genes least tolerant of losing a copy. Missense variants: 420 observed, 752.2 expected, observed/expected ratio (o/e) 0.56, 90% interval 0.51 to 0.61. Synonymous variants: 274 observed, 283.89 expected, observed/expected ratio (o/e) 0.97, 90% interval 0.87 to 1.07.
Homologues: Orthologues: macaque IGF2BP1 (100% identical), chimpanzee IGF2BP1 (99% identical), dog IGF2BP1 (99% identical), pig IGF2BP1 (99% identical), rat Igf2bp1 (99% identical), mouse Igf2bp1 (99% identical), rabbit IGF2BP1 (98% identical), guinea pig IGF2BP1 (94% identical), Drosophila melanogaster Imp (36% identical), Caenorhabditis elegans imph-1 (25% identical), Drosophila melanogaster mub (15% identical), Caenorhabditis elegans fubl-1 (14% identical), and 6 more. Paralogues in human: IGF2BP3 (74% identical), IGF2BP2 (68% identical), KHSRP (18% identical), FUBP3 (18% identical), FUBP1 (18% identical), PCBP2 (17% identical), PCBP3 (16% identical), PCBP4 (16% identical), PCBP1 (16% identical), HNRNPK (15% identical), NOVA1 (14% identical), NOVA2 (14% identical).
Diseases named in the same sentence as IGF2BP1 in open-access papers:
IGF2BP1 is named in the same sentence as 153 diseases in open-access papers, as found by Europe PMC text mining. Sharing a sentence is not in itself a finding about the gene and the disease. The quoted sentences say what the papers report.
breast cancer (58 papers, 2012 to 2026). A primary or metastatic malignant neoplasm involving the breast. "Many m6A readers have been proven to be associated with distant metastasis of breast cancer and are considered promising prognostic biomarkers and therapeutic targets for breast cancer, here IGF2BP1 and YTHDF3 are examples." (PMID 39342406, 2024). "IGF2BP1 inhibits cell proliferation by regulating the targets of mRNAs associated with breast cancer, such as binding to β-catenin mRNA and improving its stability." (PMID 36052258, 2022). "We thus plan to implement a systematic and exhaustive study as well as an experimental validation of the underlying mechanisms with respect to prognostic IGF2BP1 in breast cancer, with particular emphasis on hub genes in IGF2BP1 regulatory networks." (PMID 36092925, 2022). "Conversely, there are also a small number of studies demonstrating the tumor-protective roles of IGF2BP1 in gallbladder carcinoma, colitis-associated carcinoma, colorectal cancer, and breast carcinoma." (PMID 36249006, 2022). "Recently, the IGF2BP1 gene locus, located on the long arm of chromosome 17 (17q21.32), was found to be commonly gained and associated with poor survival probability in breast cancer and neuroblastoma." (PMID 32719445, 2021). "Survival analysis showed that IGF2BP1 is an independent prognostic factor of breast cancer, and higher expression level of IGF2BP1 is associated with shorter overall survival of breast cancer patients." (PMID 34141492, 2021). "Another RBP, the zipcode binding protein IGF2BP1, has been implicated in regulating localized expression of mRNAs involved in cell adhesion in breast cancer cells." (PMID 22956911, 2012). "Overexpression of the m6A reader IGF2BP1 is associated with breast cancer metastasis." (PMID 41219902, 2025). "Subsequently, it was reported that IGF2BP1 was overexpressed in many cancers, particularly in colorectal cancer, hepatocellular carcinoma, gallbladder cancer, and breast cancer, and is associated with a poor clinical outcome and shorter survival." (PMID 39342091, 2024). "We then systematically analyzed the expression of 22 m6A RNA regulators in breast cancer and identified that IGF2BP1 may be a key m6A RNA methylation regulator associated with OS of breast cancer patients." (PMID 34141492, 2021). "IGF2BP1 may be a key m6A RNA methylation regulator associated with OS of breast cancer patients." (PMID 34141492, 2021). "A comparison of expression levels across breast cancer subtypes revealed an upregulation of the readers IGF2BP1, IGF2BP2, and IGF2BP3 in basal cases, whereas other m6A readers manifested a more homogeneous expression across subtypes." (PMID 40918643, 2025). "In bladder cancer, breast cancer, and colon cancer, higher IGF2BP1/2/3 expression was observed in immunotherapy responders compared to non-responders, while the opposite trend was observed in melanoma." (PMID 40088376, 2025). "For example, in breast cancer, lncRNA KB-1980E6.3 stabilizes c-Myc mRNA under hypoxic conditions by interacting with the m6A reader IGF2BP1, thus maintaining the stemness of cancer stem cells." (PMID 39897038, 2025). "For example, high expression of IGF2BP1 has been found to decrease the growth and invasiveness of breast cancer." (PMID 40088376, 2025). "CircRRM2 is upregulated in breast cancer tissues, where it acts as a ceRNA to sponge miR-31-5p/miR-27b-3p and activate IGF2BP1, leading to increased tumor cell invasion and migration." (PMID 40740236, 2025). "In our study, we found the oncogenic role of IGF2BP1 in TNBC cell lines, and we also showed that high expression of IGF2BP1 was clinically correlated with metastasis in breast cancer patients." (PMID 36632454, 2023). "Myc proto-oncogene is modified by m6A and read by IGF2BP1, resulting in increased mRNA stability and maintaining breast cancer stem cell stemness." (PMID 36721236, 2023).
breast cancer (continued). "USP10 can bind to, deubiquitinate, and stabilize IGF2BP1, resulting in its higher expression level in breast cancer." (PMID 36632454, 2023). "The hypoxic lncRNA, KB-1980E6.3, interacts with IGF2BP1 to stabilize c-Myc mRNA and maintain the stemness of breast cancer cells." (PMID 37941005, 2023). "By attaching to the m6A reader IGF2BP1, which is crucial to in vivo stemness and tumorigenesis in BCSCs, LncRNA KB-1980E6.3 enhances the endurance of the c-Myc mRNA in breast cancer." (PMID 38125749, 2023). "Here, we showed that overexpression of the m6A reader IGF2BP1 was clinically correlated with metastasis in breast cancer patients." (PMID 36632454, 2023). "In breast cancer, IGF2BP1 stabilised the mRNA of c‐Myc to maintain the stemness of breast cancer cell." (PMID 38073586, 2023). "Recent studies reported that IGF2BP1 was aberrantly expressed in a wide range of tumors, including liver, lung, colon, ovarian, and breast cancers." (PMID 37559205, 2023). "For instance, decreasing IGF2BP1 enhances the abilities of proliferation and migration of metastatic breast cancer cells." (PMID 37554271, 2023). "For example, the novel lncRNA KB-1980E6.3 was identified in breast cancer stem cells under hypoxia and was suggested to maintain stemness through the lncRNA KB-1980E6.3/IGF2BP1/c-Myc axis." (PMID 35765088, 2022). "Using the expression and clinical data from the TCGA-BRCA dataset, we demonstrated that the expression of IGF2BP1 mRNA was markedly correlated with histologic type, and that molecular subtypes of breast cancer were defined by HER2 status or PAM50." (PMID 36092925, 2022). "Meanwhile, IGF2BP1/MIR210HG/miR-210 regulatory axis mediates the tumorigenesis role of MYCN in breast cancer." (PMID 35346372, 2022). "In breast cancer patients, IGF2BP1 was also validated had a higher expression compared to adjacent normal tissues." (PMID 35346372, 2022). "The suppressive effect of IGF2BP1 on breast cancer invasion and metastasis has also been revealed in humans and rats, possibly through the localization of β-actin mRNA." (PMID 36249006, 2022). "In contrast to its tumor-promoting function, IGF2BP1 has also been found to inhibit malignant tumor phenotypes and correlate with better prognosis of cancer patients in breast cancer and gallbladder cancer." (PMID 36249006, 2022). "In contrast, another group reported that IGF2BP1 was reactivated in breast cancer cells by beta-catenin, and that this interaction stabilized beta-catenin." (PMID 36092925, 2022). "In this study, we demonstrated that MIR210HG was induced by IGF2BP1 through m6A modification in breast cancer." (PMID 35346372, 2022). "LncRNA KB‐1980E6.3 enhances the stability of c‐Myc mRNA by binding to IGF2BP1, therefore maintaining breast cancer stemness under hypoxic conditions." (PMID 35608100, 2022). "In summary, MYCN functions as a transcription factor of IGF2BP1, which induces IGF2BP1 expression and promotes breast cancer progression." (PMID 35346372, 2022). "IGF2BP1’s potential promotion of tumor invasiveness and progression in breast cancer, however, remains debatable." (PMID 36092925, 2022). "A previous study indicated that lncRNA KB-1980E6.3 recruited IGF2BP1 to maintain breast cancer stem cell stemness by targeting c-Myc." (PMID 34044876, 2021). "With respect to TCGA, higher expression levels of YTHDF3, IGF2BP1 and KIAA1429 were associated with shorter OS of breast cancer patients in univariate analysis." (PMID 34141492, 2021). "A novel hypoxic long-stranded noncoding RNA KB-1980E6.3 maintains stemness in breast cancer stem cells by interacting with IGF2BP1 to promote the stability of c-Myc mRNA." (PMID 34026852, 2021). "In the survival analyses, we found that IGF2BP1 is an independent prognostic factor of breast cancer." (PMID 34141492, 2021). "More and more studies have found that IGF2BP1 is abnormally expressed in liver cancer, lung cancer, colon cancer, ovarian cancer, breast cancer, and other tumors." (PMID 34206803, 2021).
breast cancer (continued). "Further studies are needed to validate the 10 m6A-related gene signature in larger samples and confirm the roles of IGF2BP1 in breast cancer using experimental methods." (PMID 34141492, 2021). "In breast carcinoma cells, IGF2BP1 promotes the localization of E-cadherin, α-actinin, and Arp-16 at cell–cell contacts." (PMID 32967226, 2020). "IGF2BP1 is specifically decreased in metastatic breast cancer due to its highly methylated promoter; it affects the migration and proliferation of metastatic cells." (PMID 32967226, 2020). "Knockdown of IGF2BP1 in colorectal and breast cancer cell lines using the RNAi approach significantly lowered GLI1 expression in these cells." (PMID 29987229, 2018). "In contrast, IGF2BP1 was proposed to interfere with the in vitro migration of breast cancer-derived cells and enhance the formation of cell–cell contacts." (PMID 23677615, 2013). "The incidence of mammary tumors within 60 weeks was 95 % when IGF2BP1 was highly expressed, and still reached 60 % with lower relative expression of the paralogue." (PMID 23069990, 2013). "Controversially, CTNNB1 was proposed to enhance the expression of IGF2BP1 expression by positive feed-back regulation in mammary carcinoma-derived tumor cells." (PMID 23069990, 2013). "In support of this, it was reported that the transgenic expression of mouse IGF2BP1 (CRD-BP) in mammary tissue promotes the formation of primary breast carcinomas as well as metastases." (PMID 23677615, 2013). "Surprisingly, IGF2BP1 depletion in mammary carcinoma-derived T47D cells was reported to enhance cell migration whereas the opposite was observed upon the overexpression of ZBP1, the chicken ortholog of IGF2BP1." (PMID 23069990, 2013). "There is a bulk of evidence accumulated indicating that IGF2BP1 sustains MYC expression in tumor cells derived from various cancers in vitro (e.g.: mammary carcinomas; ovarian carcinomas; colorectal carcinomas)." (PMID 23069990, 2013). "Transgenic over-expression of IGF2BP1 in mice induced a high level of mammary tumours, while targeted inactivation of the Igf2bp1 gene resulted in growth retardation and impaired gut development." (PMID 22427968, 2012). "In breast cancer as well as in head and neck squamous cell carcinoma, IGF2BP1 could also up-regulate invasion and metastasis potential by regulating metastatic-related protein (MRP) and Wnt/β-catenin pathways." (PMID 40584294, 2025). "These modifications could be recognized by IGF2BP1, leading to the increase of their mRNA levels, and subsequently, metastasis of breast cancer cells." (PMID 40584294, 2025). "IGF2BP1 could also increase tumor cell ferroptosis resistance by enhancing GPX4 mRNA stability in breast cancer and NSCLC cells." (PMID 40584294, 2025). "Promoting breast cancer metastases across the USP10/IGF2BP1/CPT1A axis, it may directly identify and bind the m6A site on CPT1A mRNA, hence enhancing its stability." (PMID 39679845, 2024). "However, IGF2BP1 exhibits tumour‐suppressive characteristics in colon stromal cells and breast cancer." (PMID 39679845, 2024). "Binding of KB-1980E6.3, in turn, enhances the recognition of m6A-modified c-Myc mRNA by IGF2BP1, and hence the stability of c-Myc mRNA, thus triggering a cascade of oncogenic events, resulting in breast cancer cell stemness and tumorigenesis, both in vitro and in vivo." (PMID 36768150, 2023). "The discrepancies of IGF2BP1 function in breast cancers need to be noted." (PMID 36632454, 2023). "Acting as a scaffold, an aberrantly overexpressed lncRNA, KB-1980E6.3, interacts with the KH1-2 domain of IGF2BP1 to constitute a KB-1980E6.3/IGF2BP1/c-Myc signaling axis, which promotes the stability of c-Myc and maintains the stemness of breast cancer stem cells." (PMID 37554271, 2023).